AFP (alpha fetoprotein)
Diseases named in the same sentence as AFP in open-access papers (continued):
Sharing a sentence is not in itself a finding about the gene and the disease.
tumor (continued). "Since we have identified AFP as a tumor-associated T cell antigen for HCC, we utilized the AFP antigen in multiple forms (AdVhAFP, AFP protein, AFP-derived peptide) for DC loading." (PMID 21969837, 2011). "Human alpha-fetoprotein (AFP) is a tumor-associated fetal glycoprotein that functions in regulation of both ontogenic and oncogenic growth." (PMID 21235824, 2011). "There are only a handful of studies identifying tumor size, staging systems and α-fetoprotein (AFP) in association with these endpoints to date." (PMID 19886989, 2009). "The following parameters were found to be strongly associated with prognosis and prediction value: AFP, albumin level, venous infiltration and the number of tumor nodules." (PMID 19886989, 2009). "The aims of this study were to determine the role of AFP and hCGβ as diagnostic and prognostic markers, their relationship with other tumour markers, as well as their value in predicting disease progression in NET patients." (PMID 18577995, 2008). "Alpha-fetoprotein (P=0.153) and histological grade (P=0.148) were also associated with early tumour recurrence." (PMID 15668718, 2005). "Involvement of AFP against apoptosis of tumor cell has been implicated in its evasion of immune surveillance." (PMID 16080799, 2005). "All risk factors were predictors of survival as indicated by the Hazard ratios ranging from 2.1 to 6.2, where the tumour marker AFP was the weakest risk factor in the univariable analysis." (PMID 15026798, 2004). "There was a trend toward positive association of 8p or 13q loss with advanced tumour staging (P=0.06), and 8p loss with AFP greater than 20 ng ml−1 (P=0.06)." (PMID 12454776, 2002). "Conversely, Clusters 1 and 2, which correspond to the lowest-risk groups, are primarily distinguished by the smallest tumor size and AFP levels, along with a better preserved liver function, reflected by low bilirubin, low creatinine, and absence of ascites (Ascites_1)." (PMID 41536859, 2026). "Meanwhile, elevated AFP may suggest fetal-like tumor characteristics, potentially linked to hepatic differentiation or stem cell-like properties." (PMID 40406247, 2025). "In addition, a study involving non-small cell lung cancer patients showed that decreased expression of miR-668-3p was associated with elevated levels of AFP and other tumor markers." (PMID 40430002, 2025). "Multi-cancer screening platforms, such as OneTest, combine tumor-associated proteins (AFP, CEA, CA19-9, CA125, CA15-3, PSA, CYFRA 21-1) with clinical variables and employ models including SVM, k-nearest neighbors, Ridge Logistic Regression, MLP, and J48 decision trees to detect over 20 cancer types." (PMID 41301215, 2025). "The association between tRF‐34‐P4R8YP9LON4VHM expression and HCC patients' clinicopathological parameters was determined using tissue microarrays of 90 patients, and we found that it was positively associated with the level of AFP, tumour size, microvascular density (MVD), and TNM stage." (PMID 40263693, 2025). "Many in vitro studies have shown that AFP is associated with tumor progression and metastasis." (PMID 40857604, 2025). "Notably, the MUP-uPA mice showed evidence of profound HCC development, including an increased number of tumors, higher expression of the tumor-associated marker AFP, and elevated expression of the tumorigenesis-related genes Sqstm1 (p62) and Afp." (PMID 40257356, 2025). "Additionally, key clinical characteristics, including pathological and histological grade, AFP levels, and tumor size, showed a close association with LMNB2 expression." (PMID 40483310, 2025). "They showed that the serum AFP levels were significantly associated with the maximal tumor size." (PMID 40709064, 2025). "For AFP, a plausible explanation could be that AFP-levels are associated with tumor burden and, thereby indirectly CI as with LDH." (PMID 40526183, 2025).
tumor (continued). "Using four machine learning algorithms to predict LNM in HCC, increasing age (≥60 years), male sex, American Indian, Black, and White race, larger tumor size (3cm ≤ D < 5cm, 5cm ≤ D < 10cm, D ≥ 10cm), advanced T stage (T2, T3, T4), and positive AFP levels were identified as independent risk factors." (PMID 40718824, 2025). "Notably, despite having significantly smaller tumor diameters, this group demonstrated a higher proportion of multiple tumors and elevated AFP levels, leading to a significantly increased risk of intrahepatic and early recurrence." (PMID 40922911, 2025). "The most common predictors for OS were the underlying cause of HCC, AFP, and tumor size." (PMID 39735678, 2025). "Consequently, SERPING1 expression was significantly decreased with higher AFP levels, predicted metastasis risk signature, primary tumor size, and more advanced pathological stage of HCC." (PMID 39474998, 2025). "Utilizing an international, multi-institutional database, we developed a time-updated prediction model that integrated postoperative AFP trends with tumor burden, allowing for time-updated, dynamic risk assessments to improve recurrence prediction during outpatient follow-up." (PMID 40238062, 2025). "Furthermore, diminished AIM2 expression has been strongly linked to elevated serum alpha-fetoprotein (AFP) levels, vascular infiltration, poor tumor differentiation, incomplete tumor encapsulation, and decreased postoperative survival." (PMID 39744568, 2025). "AFP, a routinely measured tumor marker, helps assess recurrence risk during follow-up." (PMID 40238062, 2025). "In particular, high AFP levels, which are often associated with aggressive tumor behavior, may indicate a subset of patients whose tumors are more immunogenic and thus more likely to respond to the enhanced immune modulation provided by dual ICIs." (PMID 41451207, 2025). "Similarly, a higher Buffa Hypoxia Score was associated with advanced tumor stage (P < 0.0001), poorer tumor differentiation (P = 0.006), increased vascular invasion (P = 0.007), and elevated AFP levels (P = 0.027)." (PMID 41050691, 2025). "Additionally, a preoperative and postoperative ERASL model based on gender, albumin, AFP, and tumor size and number categorized the risk of HCC recurrence into high, intermediate, and low groups." (PMID 39816698, 2025). "In a study of over 1,000 liver resection samples, a nomogram incorporating seven risk factors, including tumor size, multiple nodules, and alpha-fetoprotein (AFP), achieved the best preoperative prediction of MVI in HBV-related HCC within the Milan criteria, with an AUC of 0.8014." (PMID 40730604, 2025). "One possible explanation is that higher AFP levels reflect an underlying pro-inflammatory tumor microenvironment, increased tumor antigenicity or tumor necrosis, which could potentiate immune activation and response to immunotherapy." (PMID 40387836, 2025). "Higher AFP levels are generally linked to greater tumor aggressiveness and poorer prognosis." (PMID 40430002, 2025). "In addition to conventional peripheral blood biomarkers, such as AFP, the correlation between PD-L1 expression level, tumor mutational burden (TMB), and other factors, and patient responsiveness to immunotherapy has emerged as a significant research focus." (PMID 40792280, 2025). "Similarly, prognostic risk factors such as AFP, PT and tumor volume were approximately significant, with higher AIDRS correlating with increased risk (P ≤ 0.01)." (PMID 40771801, 2025). "For instance, imaging features may overlap, and the diagnostic efficacy of commonly used tumor markers, such as alpha-fetoprotein (AFP) and carbohydrate antigen 19-9 (CA19-9), is suboptimal in certain patients." (PMID 40128070, 2025). "Tumor size and elevated alpha-fetoprotein levels are also associated with vascular invasion." (PMID 40171097, 2025). "Patients were divided into high- and low-risk groups based on MER, AFP, tumor size, and BCLC." (PMID 40075616, 2025).
tumor (continued). "In the paper, we also discuss the association between AFP and tumor-related factors." (PMID 41293148, 2025). "AFP is an important tumor-associated antigen for HCC and a potential immunotherapy target." (PMID 41514551, 2025). "High TPO levels are associated with increased tumor burden, high AFP, PVT, and poorer prognosis." (PMID 41228207, 2025). "Elevated AFP levels may not only correlate with tumor occurrence but could also reflect underlying tumor behavior, encompassing factors such as invasiveness, metastatic potential, and treatment response." (PMID 40485723, 2025). "Second, our prognostic benchmarking did not include contemporary multi‐parameter serologic scores such as GALAD or ASAP, which integrate demographic variables and multiple tumour markers and have been reported to outperform AFP alone for HCC detection and risk stratification." (PMID 41383134, 2025). "This quality of miRNAs has demonstrated favorable performance characteristics as a reliable blood-based biomarker with high diagnostic accuracy compared to current serum tumor markers (STMs), including α-fetoprotein (AFP), beta human chorionic gonadotropin (β-hCG), and lactate dehydrogenase (LDH)." (PMID 38611057, 2024). "Therefore, the combination of AFP score and tumor number is recommended to exclude high-risk listed patients and to accurately predict oncological outcome after liver transplantation." (PMID 38589847, 2024). "Elevated AFP is linked to inhibiting the programmed cell death of tumor cells, promoting their proliferation and metastasis, inhibiting the functions of lymphocytes, macrophages, and dendritic cells, inducing malignant transformation, and facilitating the onset of HCC." (PMID 38923354, 2024). "Alpha-fetoprotein (AFP) is a tumor-associated antigen in HCC." (PMID 39334927, 2024). "Our findings indicate that patients with a favorable early AFP response have a significantly reduced risk of tumor progression and a notably extended overall survival, suggesting that they may be better candidates for neoadjuvant therapy." (PMID 39767676, 2024). "HCC stands in stark contrast to other tumor types with a historic lack of proven adjuvant therapy despite known risk factors for early recurrence, including higher tumor burden, elevated alpha fetoprotein levels, microvascular invasion, and poor tumor differentiation." (PMID 38829199, 2024). "Additionally, researchers found that the higher the TUG1 concentration, the higher the AFP concentration, and an increase in AFP is associated with a larger tumour volume and a lower median survival rate for patients with HCC." (PMID 39199374, 2024). "Additionally, the AFP response should be evaluated as decreasing AFP levels in response to neoadjuvant chemotherapy have been shown to predict favourable outcomes, while poor AFP response is associated with tumour recurrence." (PMID 38304238, 2024). "Various risk factors have been reported in the literature to be associated directly with tumor recurrence after liver transplantation or resection and include high pre-transplant AFP levels, MVI, multiple tumors, large tumor size (>5cm), and a poorly differentiated subtype." (PMID 39749089, 2024). "However, with multivariate analysis, only APRI, tumor size, bilobular invasion, and AFP were identified as independent risk indicators for early TACE refractoriness." (PMID 39258671, 2024). "The hepatic venous pressure gradient (HVPG), transient elastography-liver stiffness measurement (TE-LSM), and the association between TBS (tumor burden score), alpha-fetoprotein levels, and the Child–Pugh classification (TAC score) can serve as valuable prognostic indicators for these patients." (PMID 38611104, 2024). "In addition to this, pathological features like advanced TNM staging, AFP, lymph node metastasis, and tumor size were also positively linked with the overexpression CASC9." (PMID 39448589, 2024).
tumor (continued). "However, traditional tumor biomarkers, such as serum AFP, CEA and CA19-9, have limited diagnostic capacity, sensitivity and specificity." (PMID 38366146, 2024). "Hence, it was notably linked to clinicopathological features of HCC, including AFP levels, tumor grade, and tumor size." (PMID 39062583, 2024). "In this study, high level of PDL1 was found in plasma exosomes of HCC patients, which turned out to be significantly associated with the increased number of tumor nodules, the upregulated level of serum AFP, the raised tendency of TNM stage, and the poor prognosis of HCC." (PMID 39421264, 2024). "Multivariate analyses performed based on Cox regression models to identify independent prognostic factors associated with PFS showed that AFP level, treatment method, Child–Pugh score and Number of tumor were identified as independent prognostic factors for PFS." (PMID 39474615, 2024). "This advantage may be attributed to the association between low AFP levels and smaller tumor size, improved liver function, and reduced recurrence rates." (PMID 39038010, 2024). "Next, we explored the association between early AFP response and tumor response outcomes." (PMID 39767676, 2024). "Moreover, the clinical diagnosis model combining CA50, CA19‐9, and AFP also showed better diagnostic performance than the single tumor marker." (PMID 38924330, 2024). "The expression level of AFP is associated with tumorigenesis and tumor prognosis." (PMID 38660138, 2024). "It is well known that AFP is significant risk factor for tumor aggressiveness, which may be the reason why high AFP levels seem to have a protective effect on major complications in the present study." (PMID 37875843, 2023). "Therefore, MVFC‐identified tumor mutations and AFP were combined to provide an integrated evaluation of patients' prognosis." (PMID 37496285, 2023). "In our study, the YA score with 7 risk variables covering tumor burden (tumor size and tumor number), serum tumor markers (AFP and DCP), liver function (APR), coagulation function (Fib), and gender, was established to dramatically enhance the predictive reliability." (PMID 36936655, 2023). "At 3 years, the linear model for RMST differences found that factors associated with better OS included younger age, lower AFP level, higher platelet counts, solitary tumor, tumor encapsulation, smaller tumor, better than grade 1 MVI, and better than grade 2 MVI (eTable 2 in Supplement 1)." (PMID 37906195, 2023). "Elevated AFP levels have demonstrated predictive value for various clinical outcomes, including tumor recurrence after resection, risk of drop-out in patients awaiting liver transplantation, survival rates, response to loco-regional therapies, and overall survival in advanced HCC." (PMID 37444544, 2023). "Advanced tumor stage and viral etiology were associated with elevated AFP levels." (PMID 36831565, 2023). "Thus, the risk score (R) was calculated as follow R = 5× (AFP: 0 if <400 ng/ml or 1 if ≥400 ng/ml) + 5× (albumin: 0 if >35 g/L or 1 if ≤35 g/L) + 8× (tumor size: 0 if ≤5 cm or 1 if > 5cm)." (PMID 37434986, 2023). "However, when separately using the ALBI grade, tumor burden or AFP for risk stratifications, PS remained predictive in every subgroup, indicating that these factors should not be used to identify the target candidates (all P<0.05)." (PMID 37434986, 2023). "Similarly, our study showed significance between tumor marker levels and quantitative parameters; however, a positive association was only observed with AFP levels." (PMID 37848723, 2023). "Tumor-absorbed dose is associated with OS, objective response, and alpha-fetoprotein response." (PMID 37782464, 2023). "The PFS and TTP were found to be associated with AFP levels, tumor size, dose of regorafenib, and degree of response (complete response (CR) vs. partial response (PR) vs. stable disease (SD)), while the OS was associated only with regorafenib’s dose and degree of response." (PMID 38201479, 2023).
tumor (continued). "Given the augmented risk of germ cell malignancies linked to the presence of Y chromosome material, tumour markers (human chorionic gonadotropin, alpha‐fetoprotein, and lactate dehydrogenase) were evaluated and showed negativity, albeit with a slightly elevated alpha‐fetoprotein." (PMID 37822273, 2023). "Large tumour size (p < 0.001) and higher AFP levels (p = 0.021) were independent risk factors." (PMID 37533945, 2023). "Further on, a lower decrease from the maximum AFP value to the AFP value measured before transplantation in relation to and a higher absolute AFP-value at the time of transplantation increased the risk of tumor recurrence." (PMID 36832331, 2023). "Thus, the Hangzhou criteria has already included three risk factors (tumor burden, histopathologic grade, and pre-LT AFP) identified by multivariate analysis." (PMID 37988413, 2023). "Published studies (with the exception of the most recently published ones) have been systematized into past published meta-analyses, evaluating the accuracy of HCC detection by serum determination of PIVKA II and AFP biomarkers, alone or in combination in patients at risk of tumor development." (PMID 36899960, 2023). "Considering other clinical factors such as older age, liver function impairment, vascular invasion, tumor aggressiveness, and elevated AFP are associated with HBV+ HCC survival, machine‐learning algorithm should be taken as a proper method for gene's prognostic contribution ranking." (PMID 37461802, 2023). "High expression of URI was associated with high levels of tumor marker α-fetoprotein (AFP)." (PMID 37805657, 2023). "As the most established biomarker in HCC, higher serum AFP levels have been associated with increased tumor aggressiveness (e.g., worse tumor differentiation, increased incidence of microvascular invasion, macrotrabecular-massive subtype, proliferative HCC), and worse posttreatment prognosis." (PMID 36617583, 2023). "In addition, AFP is associated with angiogenesis, hampers anti-tumor immunity, and facilitates tumor proliferation." (PMID 37268978, 2023). "In this study, AFP was a risk factor of tumor recurrence after curative liver resection of HCC." (PMID 37007138, 2023). "The combination of MVFC‐identified tumor mutations and Alpha Fetoprotein (AFP) could further improve MRD detection (P < 0.0001)." (PMID 37496285, 2023). "AFP can promote tumor growth partly by the inhibition of apoptosis; besides, it was also associated with the upregulation of vascular endothelial growth factor signaling, thereby promoting tumor angiogenesis and metastasis." (PMID 37191923, 2023). "The use of <3 lines, the non-complete and partial response of the first line, modified albumin–bilirubin at grade 2b or 3, an intrahepatic tumor number ≥ 5, extrahepatic metastasis, and alpha-fetoprotein at ≥400 ng/mL were the strongest factors associated with shorter OS." (PMID 37958471, 2023). "These tumor antigens are the primary targets used in ACT for HCC and mainly fall into one of the three categories, including tumor-associated antigens (e.g., AFP, GPC-3), viral-derived cancer antigens (VHB, VHC), and cancer–testis antigens (e.g., NY-ESO-1, MAGE)." (PMID 36980692, 2023). "In patients with surgically-confirmed solitary HCC ≤ 5 cm, we found that two EOB-MR imaging features (marked hepatobiliary phase hypointensity and the LR-M category) along with serum AFP > 400 ng/mL were significantly associated with poor tumor differentiation." (PMID 36617583, 2023). "Taxol administration in the current research caused mRNA overexpression of tumor marker AFP." (PMID 37466839, 2023). "In multivariate analysis the independent risk factors for HCC recurrence were AFP >400 ng/mL (HR = 1.47, 95% CI: 1.69–2.31, P = 0.01), moderate/poor differentiated tumor (HR = 3.06, 95% CI: 2.58–6.29, P = 0.02), and microvascular invasion (HR = 2.51, 95% CI: 1.05–1.93, P = 0.01)." (PMID 36268362, 2022).